SP4 (Sp4 transcription factor)
Diseases named in the same sentence as SP4 in open-access papers (continued):
Sharing a sentence is not in itself a finding about the gene and the disease.
colon cancer (11 papers, 2011 to 2024). "Mechanistic studies suggest that sulindac sulfide induces reactive oxygen species (ROS) which in turn downregulates expression of Sp1, Sp3 and Sp4 in colon cancer cells." (PMID 26673922, 2015). "We further assessed the involvement of the pro-oncogenic specificity protein (Sp) transcription factors Sp1, Sp3, and Sp4 in the antileukemic effect of high AA because high AA exhibits anticancer activity towards colon cancer cells." (PMID 23626851, 2013). "Further, the expression of Sp1, Sp3, and Sp4 was also downregulated by high AA in K562 cells, as was observed in colon cancer cells." (PMID 23626851, 2013). "We further assessed the involvement of Sp1, Sp3, and Sp4 in the antileukemic effect of high AA because high AA exhibits anticancer activity towards colon cancer cells, which is due in part to downregulation of Sp transcription factors and Sp-regulated genes." (PMID 23626851, 2013). "Results of this study has identified a novel pathway for aspirin-induced effects on Sp1, Sp3 and Sp4 in colon cancer cells, and current studies are focused on specific enzymes and pathways associated with the effects of aspirin on zinc homeostasis." (PMID 23110215, 2012). "Colon cancer cell growth inhibition was accompanied by downregulation of Sp1, Sp3 and Sp4 proteins and decreased expression of Sp-regulated gene products including bcl-2, survivin, VEGF, VEGFR1, cyclin D1, c-MET and p65 (NFκB)." (PMID 23110215, 2012). "Since NFκB (p65) and the β-catenin promoters contain GC-rich Sp binding sites, we used RNAi to determine the role of Sp1, Sp3 and Sp4 in regulation of p65, p50 and β-catenin in colon cancer cells." (PMID 23110215, 2012). "In summary, we have shown that the anticancer activity of BA in colon cancer cells is due, in part, to downregulation of Sp1, Sp3, Sp4 and Sp-regulated prooncogenic gene products." (PMID 21864401, 2011). "Previous studies show that BA induces proteasome-dependent degradation of specificity protein (Sp) transcription factors Sp1, Sp3 and Sp4 in prostate cancer cells and this study focused on the mechanism of action of BA in colon cancer cells." (PMID 21864401, 2011). "Moreover, in HT-29 colon cancer cells, quercetin–resveratrol combination treatment reduced the proteins SP1, SP3, and SP4, transcription factors known to be overexpressed in colon cancer." (PMID 37373289, 2023). "SP1 and SP4 are essential for colon cancer cells and knockdown of them may induce apoptosis in cancer cells." (PMID 31500382, 2019). "This study demonstrates that sulindac sulfide, the active metabolite of sulindac which is known to exhibit anti-neoplastic activity in human and experimental models of colon cancer, also downregulates Sp1, Sp3, Sp4 and pro-oncogenic Sp-regulated genes in colon cancer cells." (PMID 26673922, 2015). "In summary, this study demonstrates that aspirin induces caspase-dependent proteolysis of Sp1, Sp3 and Sp4 proteins in colon cancer cells and tumors and, this was accompanied by downregulation of several Sp-regulated genes involved in cell proliferation, survival and angiogenesis." (PMID 23110215, 2012). "Thus, pharmacologic doses of aspirin that give low mM serum concentrations can be accompanied by >30-fold higher concentrations of salicylate which are more than sufficient to inhibit colon cancer cell growth and decrease Sp1, Sp3, Sp4 and Sp-regulated genes." (PMID 23110215, 2012). "Moreover, knockdown of Sp1, Sp3 and Sp4 (in combination) in RKO colon cancer cells also decreased expression of EGFR, cyclin D1, p65 and PTTG-1, confirming the role of Sp transcription factors in regulating expression of these genes." (PMID 21864401, 2011). "Since overexpression of ZBTB10 and antisense-miR-27a also decreases expression of Sp1, Sp3, Sp4 and Sp-regulated genes in colon cancer cells, the mechanism of action of BA in RKO cells is linked to disruption of miR-27a:ZBTB10 as previously reported for CDODA-Me and GT-094 in colon cancer cells." (PMID 21864401, 2011).
colon cancer (continued). "Sp1 and also Sp3 and Sp4 are highly expressed in cancer cells and in this study, we have used results of RNA interference (RNAi) to show that the three TFs individually play a role in the growth, survival and migration/invasion of breast, kidney, pancreatic, lung and colon cancer cell lines." (PMID 26967243, 2016). "Colon cancer patients on low dose aspirin therapy (75 mg/d; ca. 1 mg/kg/d) would exhibit maximum average serum concentrations of salicylate (6.8 mM) and aspirin (0.21 mM) sufficient to inhibit colon cancer cell growth and decrease expression of Sp1, Sp3, Sp4 and Sp-regulated genes." (PMID 23110215, 2012). "Moreover, in HT-29 colon cancer cells, treatment with quercetin in combination with resveratrol resulted in decreased SP1, SP3 and SP4 proteins, transcription factors known to be overexpressed in colon cancer." (PMID 27681738, 2016). "Moreover combined knockdown of Sp1, Sp3 and Sp4 using an oligonucleotide cocktail (iSp) also decreased expression of p65, PTTG-1, EGFR and cyclin D1 in RKO cells confirming their regulation by Sp transcription factors in colon cancer cells." (PMID 21864401, 2011).
pancreatic cancer (8 papers, 2012 to 2025). "The transcription factors Sp1, Sp3 and Sp4 are overexpressed in pancreatic cancer cells and like MALAT-1, knockdown of Sp1, Sp3 and Sp4 or Sp1/Sp3/Sp4 (combined) results in decreased cell growth, induces apoptosis, and decreases migration." (PMID 29389953, 2018). "We observed high expression of Sp1, Sp3 and Sp4 in pancreatic tumors from these mice, whereas low expression of these proteins has been reported in normal mouse tissues." (PMID 29389953, 2018). "We also observed that tumor growth in mice bearing L3.6pL pancreatic cancer cells depleted of Sp1 or Sp1, Sp3 and Sp4 (combined) was significantly lower than observed in studies using wild-type cells expressing these TFs." (PMID 26967243, 2016). "The antidiabetic drug metformin decreases expression of Sp1, Sp3, Sp4 and Sp-regulated genes in pancreatic cancer cells and metformin (0–20 mM) inhibited growth of HepG2, SNU-449 and SK-Hep-1 cells after treatment for 24 and 48 hr." (PMID 26317792, 2015). "Metformin is an antidiabetic drug that protects patients against pancreatic cancer and metformin downregulates Sp1, Sp3, Sp4 and pro-oncogenic Sp-regulated genes in pancreatic cancer cells and tumors." (PMID 26317792, 2015). "Tolfenamic acid induces proteasome-dependent downregulation of Sp1, Sp3 and Sp4 in pancreatic cancer cells." (PMID 26673922, 2015). "Curcumin inhibits growth of several cancer cell lines, and studies in this laboratory in bladder and pancreatic cancer cells show that curcumin downregulates specificity protein (Sp) transcription factors Sp1, Sp3 and Sp4 and pro-oncogenic Sp-regulated genes." (PMID 23194063, 2012). "In bladder cancer cells, curcumin induced proteasome-dependent downregulation of Sp1, Sp3 and Sp4, whereas in pancreatic cancer cells this response was ROS-dependent and reversed by cotreatment with antioxidants such as GSH." (PMID 23194063, 2012). "Recent studies show that HuR and IDH-1 were regulated by NR4A2/Sp4 in pancreatic cancer cells." (PMID 39858066, 2025). "This was consistent with studies in this laboratory showing that CDDO-Me induced ROS and ROS-dependent downregulation of Sp1, Sp3 and Sp4 and pro-oncogenic Sp-regulated genes and has been observed with other ROS-inducing anticancer agents in pancreatic cancer cells." (PMID 29389953, 2018). "Moreover, tumor growth in athymic nude mice bearing L3.6pL pancreatic cancer cells as xenografts were significantly decreased in cells depleted for Sp1, Sp3 and Sp4 (combined) or Sp1 alone." (PMID 26967243, 2016). "Studies in this laboratory have shown that curcumin inhibits bladder and pancreatic cancer cell and tumor growth and that the anticancer activity is due, in part, to downregulation of specificity protein (Sp) transcription factors Sp1, Sp3, Sp4 and Sp-regulated genes." (PMID 23194063, 2012). "Sp transcription factors Sp1, Sp3 and Sp4 are highly expressed in cancer cells/tumors and Sp1 is a negative prognostic factor for survival of gastric and pancreatic cancer and glioma patients." (PMID 26673922, 2015).
bipolar disorder (6 papers, 2009 to 2025). A disorder of the brain that causes unusual shifts in mood, energy, activity levels and the ability to carry out day-to-day tasks. "Considering significant genetic association between SP4 gene and bipolar disorder, we also examined the effects of different mood stabilizers on the reversal of PPI deficits in mutant mice." (PMID 19401786, 2009). "Out of ten SNPs selected from human SP4 genomic locus, four displayed significant association with bipolar disorder in European Caucasian families (rs12668354, p = 0.022; rs12673091, p = 0.0005; rs3735440, p = 0.019; rs11974306, p = 0.018)." (PMID 19401786, 2009). "Of these genome linkage studies, we were particularly interested in the finding that one locus on chromosome 7, at the marker D7S1802, was found to associate with bipolar disorder, which is about 700 kb away from the SP4 gene." (PMID 19401786, 2009). "Sp4 level was increased in the brains of AD patients and reduced in the brains of bipolar disorder patients." (PMID 33424550, 2020). "Phosphorylation of SP4 at S770 is increased in the cerebellum of bipolar disorder subjects and upon inhibition of NMDA receptor signaling in cultured neurons." (PMID 25915526, 2015). "We can assume that dysregulation of STIM1-mediated SOCE may induce abnormal Sp4 expression and promote the development of disorders such as bipolar disorder or AD." (PMID 33424550, 2020). "Notably, relative levels of phosphoSp4 (pSp4) are increased in the postmortem cerebellum of bipolar disorder subjects and, in this context, SP4 S770 phosphorylation and total SP4 immunoreactivity showed an inverse correlation." (PMID 25915526, 2015). "SP4 phosphorylation and protein abundance display an inverse correlation in the cerebellum of bipolar disorder patients and in cerebellar granule neurons under depolarizing or non-depolarizing conditions suggesting that maybe lithium could reduce SP4 phosphorylation." (PMID 25915526, 2015).
bladder cancer (6 papers, 2011 to 2025). "Arsenic trioxide also induced caspase-dependent cleavage of Sp3 and Sp4 in bladder cancer cells and retinoid (CD437)-induced Sp1 degradation was also caspase-dependent in EL-4 cells." (PMID 23110215, 2012). "ROS and hydrogen peroxide (H2O2) play a role in downregulation of Sp1, Sp3 and Sp4 in pancreatic and bladder cancer cells and treatment of RKO cells with BA for 36 h induced ROS as determined by FACS analysis using the fluorescent ROS scavenger H2DCFDA." (PMID 21864401, 2011). "Previous studies showed that BA-induced downregulation of Sp1, Sp3 and Sp4 was proteasome-dependent in LNCaP cells but proteasome-independent in KU7 bladder cancer cells." (PMID 21864401, 2011). "In contrast, EV samples derived from both GCB‐sensitive and GCB‐resistant bladder cancer cell lines, including SP3 (T24 EVs), SP4 (T24GCB EVs), SP5 (5637 EVs) and SP6 (5637GCB EVs), showed no detectable GCB signal." (PMID 41159684, 2025). "For example, knockdown of Sp1 (siSp1) or Sp3 (siSp3) in 253JB-V bladder cancer cells decreased expression of Sp4 protein, whereas siSp4 did not affect levels of Sp3 or Sp1 proteins." (PMID 26967243, 2016). "Previous studies demonstrated high specificity for knockdown of Sp1, Sp3 and Sp4 by RNAi in RD rhabdomyosarcoma and KU7 bladder cancer cells, whereas in other cell lines, knockdown of an individual Sp protein also decreased expression of one or both of the other gene products." (PMID 26967243, 2016).
colorectal cancer (6 papers, 2020 to 2025). A primary or metastatic malignant neoplasm that affects the colon or rectum. "Moreover, a short 130-aa peptide SRSP encoded by LOC90024 contributes to colorectal cancer development by promoting the binding of SRSF3 to Sp4 transcription factor." (PMID 37285335, 2023). "This interaction promotes the production of an oncogenic long SP4 isoform (L-SP4) and drives colorectal cancer (CRC) progression." (PMID 41291707, 2025). "Apart from SP4, EGR1, ARID3A, and NKX6-1, the remaining transcription factors have been reported in colorectal cancer, which supports the importance of these candidate DEMs in the mechanism of CRC tumor." (PMID 36798788, 2023). "In colorectal cancer, SRSF3 interacts with the small splice-regulating protein SRSP, mediating selective splicing of SP4 to produce cancerous SP4 subtypes, which leads to tumor occurrence and metastasis." (PMID 33854615, 2021).
prostate carcinoma (4 papers, 2009 to 2021). A carcinoma that arises from epithelial cells of the prostate gland. "Studies in this laboratory show that BA inhibits prostate cancer cell and tumor (xenograft) growth and this is due, in part, to proteasome-dependent downregulation of Sp1, Sp3, Sp4 and several Sp-regulated genes." (PMID 21864401, 2011). "Previous studies in this laboratory showed that BA inhibits prostate cancer cell and tumor growth and this is accompanied by proteasome-dependent degradation of Sp1, Sp3 and Sp4 and several Sp-regulated pro-oncogenic gene products." (PMID 21864401, 2011). "Similarly, ZBTB4 can transcriptionally inhibit specific protein transcription factors (Sp1, Sp3, and Sp4), thereby inhibiting the proliferation of prostate cancer cells and promoting cell apoptosis." (PMID 34047477, 2021).
rhabdomyosarcoma (4 papers, 2016 to 2024). A rare aggressive malignant mesenchymal neoplasm arising from skeletal muscle. "Studies on normal cell transformation into cancer cell lines show that this transformation process is accompanied by increased levels of Sp1 in most cell models, and in the transformation of muscle cells into rhabdomyosarcoma, both Sp1 and Sp3, but not Sp4, are increased." (PMID 36982239, 2023). "Inhibition of SP family (SP1, SP3 and SP4) could suppress rhabdomyosarcoma cell and tumor growth via non-steroidal anti-inflammatory drug (NSAID) tolfenamic acid (TA)." (PMID 35847857, 2022). "Rhabdomyosarcomas (RMS) express high levels of Sp1 compared to non-transformed muscle tissue and RMS cell lines express high levels of Sp1, Sp3 and Sp4." (PMID 36982239, 2023).
dermatomyositis (3 papers, 2024). Dermatomyositis (DM) is a type of idiopathic inflammatory myopathy characterized by evocative skin lesions and symmetrical proximal muscle weakness. "Additionally, a new autoantigen, the transcription factor Sp4, has been identified as being associated with an increased risk of cancer in patients with dermatomyositis (DM)." (PMID 39295784, 2024). "In anti-TIF1γ positive dermatomyositis (DM) patients from the USA, anti-Sp4 and anti-CCAR1 autoantibody frequencies are reported as 32% and 43% in adults and 9% and 19% in juveniles, respectively." (PMID 39514366, 2024).
glioma (3 papers, 2009 to 2019). A benign or malignant brain and spinal cord tumor that arises from glial cells (astrocytes, oligodendrocytes, ependymal cells). "Furthermore, high expression of Sp4 or ANGPTL4 significantly associated with high risk of glioma, and contributed to poor survival in GBM patients." (PMID 31717924, 2019). "Among the members of the Sp family, both Sp1 and Sp4 were obviously increased in brain tumors, and Sp1 has been shown to promote glioma progression and drug resistance in numerous studies." (PMID 31717924, 2019). "In 12 normal brain tissue samples, Sp4 expression was negative; among 36 malignant glioma specimens including 28 astrocytomas, 4 glioblastomas and 4 oligodendrogliomas, Sp4 was positive in 21 specimens (58.33%), indicating that Sp4 expression is significantly increased in glioma." (PMID 31717924, 2019).
hepatocellular carcinoma (3 papers, 1976 to 2025). A malignant tumor that arises from hepatocytes. "Tat-SP4 also exerted a potent anti-proliferative effect in several cancer cell lines, including triple-negative breast cancer (TNBC), pancreatic ductal adenocarcinoma (PDAC), hepatocellular carcinoma (HCC), and non-small-cell lung cancer (NSCLC)." (PMID 41471037, 2025).
liver cancer (3 papers, 2015 to 2025). An epithelial or non-epithelial malignant neoplasm that arises from the liver. "Regulation of HULC by Sp1, Sp3 and Sp4 in liver cancer cells was investigated by RNAi with oligonucleotides that targeted the individual Sp transcription factors." (PMID 26317792, 2015). "Our previous studies showed that one lead candidate, Tat-SP4, induced autophagy and inhibited cell proliferation in several cancer types, including TNBC, ovarian cancer, liver cancer, and NSCLC." (PMID 41471037, 2025). "RNA interference (RNAi) studies showed that among several lncRNAs expressed in HepG2, SNU-449 and SK-Hep-1 cells, highly upregulated in liver cancer (HULC) was regulated not only by Sp1 but also Sp3 and Sp4 in the three cell lines." (PMID 26317792, 2015).
melanoma (3 papers, 2009 to 2021). A malignant, usually aggressive tumor composed of atypical, neoplastic melanocytes. "HIF-1α and c-myc are important transcription factors for the extrahepatic regulation of ASS, and the interplay between HIF-1α, c-myc, and Sp4 determines the expression of ASS in melanoma cells in the context of varying degrees of arginine availability." (PMID 28791021, 2017).
Arrhythmia (2 papers, 2011 to 2024). Any cardiac rhythm other than the normal sinus rhythm. "The LmnaN195K/N195K mice model showed the mislocation of transcription factor Hf1b/Sp4, loss of sarcomere function, and reduced lifespan to arrhythmia." (PMID 39202453, 2024). "Importantly, Sp4 -/- null mice appear to be predisposed to cardiac arrhythmias leading to sudden death." (PMID 21645329, 2011).
autoimmune disease (2 papers, 2011 to 2017). A disorder resulting from loss of function or tissue destruction of an organ or multiple organs, arising from humoral or cellular immune responses of the individual to their own tissue constituents. "During this maturation process, a transition from SP3 to SP4 was found to be critical as a blockage of this transition in Aire-/- and Relb-/- mice is associated with high incidence of autoimmune diseases." (PMID 22022412, 2011).
non-small cell lung carcinoma (2 papers, 2023). A group of at least three distinct histological types of lung cancer, including non-small cell squamous cell carcinoma, adenocarcinoma, and large cell carcinoma. "Tat-SP4 also synergized with erlotinib to potently inhibit the proliferation of non-small-cell lung cancer cell lines A549 and H1975 by degrading the over-expressed EGFR and inducing non-apoptotic cell death." (PMID 36765914, 2023).
allergic disease (1 paper, 2012). An immune response that occurs following re-exposure to an innocuous antigen, and that requires the presence of existing antibodies against that antigen. "The most highly expressed SP4 isoform is likely to contribute to MC aggregation and longevity in mastocytosis, and augment the pathophysiology of allergic diseases." (PMID 22438059, 2012).
Alzheimer disease (1 paper, 2014). A progressive, neurodegenerative disease characterized by loss of function and death of nerve cells in several areas of the brain leading to loss of cognitive function such as memory and language. "On the other hand, Sp4 levels are dramatically increased and associated with neurofibrillary tangles and pathological tau presence in neurons of the CA1 hippocampus region and entorhinal cortex of Alzheimer disease patients." (PMID 25018677, 2014).
asthma (1 paper, 2021). "Moreover, rs72891545, the most significant association signal with asthma exacerbations, has also been predicted to involve the modification of several transcription factor binding sites (ELF1, Myc, Sp4, YY1, Zfx)." (PMID 34442380, 2021).